ENSG00000262633 (novel protein)
Gene: Protein-coding gene on chromosome 17 (46,923,133 to 47,049,932, forward strand). Ensembl gene ENSG00000262633.
Genetic constraint (gnomAD): Missense variants: 150 observed, 149.51 expected, observed/expected ratio (o/e) 1, 90% interval 0.88 to 1.15. Synonymous variants: 49 observed, 55.09 expected, observed/expected ratio (o/e) 0.89, 90% interval 0.71 to 1.13.